IL1B (interleukin 1 beta)
Diseases named in the same sentence as IL1B in open-access papers (continued):
Sharing a sentence is not in itself a finding about the gene and the disease.
Obesity (continued). "Conversely, obesity is associated with increased IL-6, TNF-α, and IL-1β levels, creating a pro-inflammatory state that could contribute to depressive symptoms." (PMID 41375608, 2025). "In conclusion, inhibition of the NLRP3 inflammasome–IL-1β pathway in obesity and type 2 diabetes may represent an attractive way to target the pathogenesis of these diseases and their complications." (PMID 39496966, 2025). "The NPC degeneration model was established using PA and IL‐1β to mimic obesity‐related IVDD." (PMID 40090836, 2025). "IL-1β concentrations did not significantly differ between groups, possibly due to its close association with obesity-related inflammation." (PMID 40004007, 2025). "Since IL1B expression levels were upregulated in obesity, and the ACM also increased its expression levels in the colon adenocarcinoma HT-29 cell line, we aimed to further study its implication in obesity-associated CC." (PMID 39305371, 2025). "For example, obesity, inflammaging, cardiovascular disease, hypertension, and rheumatoid arthritis are characterized by elevated concentrations of circulating cytokines, such as IL-1b, IL-6, IL-8, IL-10, IL-13, TNF-α, and IFN-γ." (PMID 39408907, 2024). "This discovery aligns with the observation that intermittent energy restriction may effectively reduce obesity-related inflammation (including IL-1β and IFN-γ) and enhance insulin sensitivity compared to continuous energy restriction." (PMID 38622732, 2024). "Both TNFα and Il-1β were found to be able to influence insulin signaling, although it was also shown that circulating level of TNFα is lower than the effective concentration even in patients with obesity." (PMID 39004641, 2024). "Additionally, an initiation of inflammatory cascade in obesity via M1 macrophage that contributes to increased M1 macrophage markers, IL-1β and iNOS, leading to increased systemic inflammation and then affects muscle mass production." (PMID 38755201, 2024). "Both clinical and experimental studies have demonstrated that adipose tissue macrophages (ATMs) secrete pro-inflammatory cytokines, including interleukin-1β (IL-1β) and IL-18, which are essential factors in the progression of obesity-related metabolic disorders." (PMID 39351493, 2024). "This inhibition was associated with reduced levels of pro-inflammatory cytokines, including interleukin 6 (Il6), tumor necrosis factor-alpha (Tnfα), and interleukin 1beta (Il1β), underscoring the potential of TC extract as a therapeutic intervention for mitigating obesity-induced inflammation." (PMID 39683572, 2024). "Thus, when we evaluated the inflammatory response, in parallel to the systemic stress response, elevated circulating concentrations of IL-1β were found in the present high-fat diet-induced obesity model." (PMID 39064652, 2024). "Oxidative stress and chronic inflammation may be increased with obesity, as well as the levels of IL-1β, IL-6 and TNF-α, which contribute to the development of lung injury." (PMID 38650653, 2024). "This suggests that IL-1β-mediated inflammation could be related to the patient’s metabolic context, where obesity could exacerbate inflammatory activity in the tumor microenvironment." (PMID 39766795, 2024). "To determine how obesity affects neuroinflammation in female mice, we examined the mRNA expression levels of proinflammatory cytokines (TNFα, IL1β, and IL6) and markers of microgliosis (Iba1) and astrogliosis (GFAP) in three distinct brain subregions (hypothalamus, hippocampus, and cerebral cortex)." (PMID 39230054, 2024). "IL-1β expression is upregulated during obesity and is strongly related to a high-fat diet." (PMID 39606781, 2024). "In contrast, Il1b gene expression was not induced by the applied diets either in the WAT or in the BAT but the protein was present in higher concentrations in the blood of animals with obesity compared with the control group, suggesting other potential sources of circulating Il-1β." (PMID 39004641, 2024).
Obesity (continued). "Similarly, IL-1β is a pivotal mediator in inflammatory processes and has been shown to play a significant role in obesity-related inflammation, contributing to insulin resistance and β-cells’ dysfunction in diabetes." (PMID 39125408, 2024). "Thus, the authors suggested that IL-1β promotes ectopic fat deposition in hepatocytes, which, in turn, leads to the exacerbation of the metabolic syndrome observed in obesity." (PMID 39404367, 2024). "Obesity-induced increases in leptin levels may contribute to heightened inflammation and more severe symptoms through its interaction with interleukin-1 β (IL-1β)." (PMID 38790590, 2024). "The levels of TNF-α, IL-1β, and IL-6 are elevated in obesity." (PMID 39063610, 2024). "For instance, elevated levels of IL-6 have been positively correlated with the expansion of adipose tissue.TNF-α, IL-6, and IL-1β can enhance the inflammatory cascade reaction and promote inflammatory responses, which are considered key triggering factors for obesity-related complications." (PMID 38453770, 2024). "Endotoxins such as LPS intensify the damage of gut barrier proteins (such as ZO1) and induce TLR4 signaling 24, consequently promoting the production of pro-inflammatory cytokines (such as IL1β), which exacerbate systemic low-grade inflammation and accelerate obesity pathogenesis 26–28." (PMID 38956395, 2024). "Previous studies have identified IL-1β as a source of inflammatory response in human adipose tissue, particularly its subcutaneous depot, and there is evidence that the IL-1 system is involved in the initiation of obesity in general." (PMID 39590595, 2024). "Furthermore, the observed significant reductions with comparatively large effect sizes in PBMC gene expressions of IL-6, IL-1β, and leptin suggest the potential for controlled inflammation in obesity after NS oil supplementation." (PMID 38178093, 2024). "The inclusion of internal peripheral markers that reflect the body’s response to the measured health outcomes (e.g., IL1B and obesity) could also reinforce this phenomenon." (PMID 38783062, 2024). "The reduction in the mRNA levels of pro-inflammatory cytokines (TNF-α, IL-6, and IL-1β) signifies a robust anti-inflammatory effect of CME, offering a potential mechanism for its protective role against hepatic inflammation associated with obesity." (PMID 38999918, 2024). "An association between obesity and OA is related not only to the increased biomechanical overload, but also to the systemic effects of obesity, including low-grade inflammation with increased levels of proinflammatory cytokines (IL-1β, TNF-α, and IL-6) and reactive oxygen species, etc.." (PMID 38791302, 2024). "Obesity manifests with heightened inflammation levels characterized by immune cell infiltration, notably macrophage infiltration, and the increased secretion of pro-inflammatory cytokines such as IL-1β and IL-6 within adipose tissue." (PMID 38672517, 2024). "However, chronically elevated levels of IL-1β, as seen in obesity, desensitize progenitor cells to these potentially beneficial effects of IL-1β, and instead exacerbate inflammation." (PMID 39261467, 2024). "In fact, the activation of NLRP3 inflammasome in adipose tissues, whether in adipocytes or macrophages, is similar to the development of obesity and leads to production of IL-1β, which participates in the formation and development of IR." (PMID 36993972, 2023). "Systemically, increased adipose tissue accumulation, as seen in obesity, can lead to increased production of interleukin 6 (IL-6), interleukin IL-1β (IL-1β) and tumor necrosis factor (TNF-α), pro-inflammatory cytokines able to disrupt the immune response at the maternal–fetal interface." (PMID 37111410, 2023). "Thus, alimentary-induced obesity enhanced the release of pro-inflammatory cytokines, namely IL-1β and IL-6, into the blood." (PMID 37892420, 2023).
Obesity (continued). "Likewise, IL-1β is an important regulator of inflammation during obesity as its neutralisation ameliorates obesity-induced inflammation." (PMID 36175539, 2023). "Furthermore, a complex interaction between inflammation and NAFLD has been shown among children with obesity, for which inflammatory cytokines, such as IL-1β, IL-6 and IL-17, have been recently described as markers for NAFLD risk." (PMID 36837520, 2023). "Moreover, considering that chronic inflammation is associated with obesity and can further worsen IR, we measured the levels of TNF-α, IL-1β, and IL-6 in visceral adipose tissue." (PMID 37513467, 2023). "IL-1B is also involved in the genetic background of diabetes, obesity, and lung cancer prognosis." (PMID 36685671, 2023). "Other factors can influence hepcidin level in obesity, such as IL-10, IL-1β and miRNA-122." (PMID 38140340, 2023). "Given that obesity-related increase in NLRP3 inflammasome activation is a predominant regulator of IL-1β production and decreased health span, we next tested whether SPARC gain of function impacts the inflammasome." (PMID 37781916, 2023). "Obesity is characterized by chronic low-grade inflammation, which is driven by macrophage infiltration in adipose tissue and leads to elevated cytokines such as interleukin-1β (IL-1β) in the circulation and tissues." (PMID 38070059, 2023). "Furthermore, IL-1β is a critical pathological mediator of obesity-induced insulin resistance, and NLRP3 expression depends on NF-κB." (PMID 36902133, 2023). "Moreover, a recent report identified HIF-1α activation in ATMs responsible for local and systemic IL-1β maintained production under obesity conditions through ceramides sensing." (PMID 37819510, 2023). "Indeed, LPS-treatment and obesity state increased TNFα, IL-1β, and IL-6 expression, both at mRNA and protein levels, in type I TBC." (PMID 37373472, 2023). "Furthermore, IL-1 receptor I deficient mice have improved glucose tolerance and reduced inflammation in obesity, suggesting that macrophage production of IL-1β is a critical inflammatory driver in obesity." (PMID 37276236, 2023). "IL-1β contributes to the development of insulin resistance that accompanies obesity." (PMID 36835557, 2023). "Adipocytes recruit and excite macrophages through the CCL2/IL-1β/CXCL12 pathway during obesity." (PMID 36593475, 2023). "Obesity is associated with an increase in the secretion of adipocytokines, such as TNF-α, leptin, resistin, IL-1β or IL-6, by immune cells as well as adipocytes, which leads to the progress of insulin resistance through a number of processes, including the activation of Ser/Thr kinases." (PMID 36826001, 2023). "In a genetic model of obesity, leptin-receptor-deficient db/db mice exhibited increased microglia activation (Iba1 measurements) with MHCII immunoreactivity and increased levels of IL-1β in the hippocampus." (PMID 36677011, 2023). "Among them, IL-6 and IL-1β are crucial for obesity-related HCC." (PMID 37266440, 2023). "In Pancreatic ductal adenocarcinoma (PDAC) mouse models, adipocyte-secreted IL-1β could promote obesity-induced pancreatic carcinogenesis and drug resistance through recruitment of tumor-associated neutrophils." (PMID 36899319, 2023). "Animal studies have emphasized that obesity is associated with adipose tissue inflammation and oxidative stress in the liver, and certain Lactobacillus strains can reduce the transcription of proinflammatory cytokine genes, such as IL-6, TNF-α and IL-1β." (PMID 36345438, 2022). "We hypothesised, that this mechanism might contribute to the activation of adipose tissue (AT) in obesity, and investigated [Ca2+]ex-induced, CaSR mediated IL-1β release by macrophages in obesity." (PMID 35931812, 2022). "Therefore, we performed TNF-α, IL-1β, and IL-6 mRNA expression analysis in the bone, in order to investigate the impact of D-gal-induced aging and obesity on bone inflammatory status." (PMID 35595806, 2022).
Obesity (continued). "Likewise, low-grade chronic inflammation associated with obesity and the subsequent increase in pro-inflammatory cytokine secretion is associated with insulin resistance, with TNF-α, IL-1β, and IL-6 directly impairing insulin signal transduction." (PMID 35883605, 2022). "Similarly, at the visceral adipose tissue level, HFD-induced obesity led to an up-regulation of the production of IL-1β, IL-6, TNF-α and MCP-1 as well as leptin and adiponectin." (PMID 35624723, 2022). "Insulin resistance and vitamin D deficiency related to obesity may aggravate airway remodeling and hyper-responsiveness by enhancing leptin, transforming growth factor (TGF)-β1, IL-1β, and IL-6 expression, which might then promote neutrophilic inflammation." (PMID 35626330, 2022). "IL-1β plays a vital role on lipid metabolism via regulating lipase activity and negatively adjusts cartilage, there are reports of an association between IL-1β and obesity independent of population." (PMID 36575508, 2022). "In addition, obesity causes a pro-inflammatory state with the release of several mediators like TNF- α, IL-6, and IL-1β, promoting tumor growth." (PMID 35937803, 2022). "Alternatively, obesity is associated with higher CRP via an increased mechanical load placed on joints, leading to ‘wear and tear’ and increased expression of the pro-inflammatory cytokines (e.g., IL-1β and TNF-α) which promote CRP production." (PMID 35301057, 2022). "Under obesity, IL-1β from primary adipocytes could induce the angiopoietin-like 4 (ANGPTL4) expression through activation of NF-κB and mitogen-activated protein (MAP) kinases, therefore promoting angiogenesis and tumor suppression." (PMID 35701840, 2022). "Based on the finding of an increased exCa2+-induced IL-1ß response of macrophages derived from peripheral blood monocyte from individuals with obesity, we investigated the [Ca2+]ex-induced IL-1β release in subcutaneous and visceral AT samples obtained from patients undergoing bariatric surgery." (PMID 35931812, 2022). "We report here, that macrophages in obesity also respond with [Ca2+]ex-induced IL-1β release." (PMID 35931812, 2022). "Considering that both cell lines are directly influenced by the inflammatory state that is observed in obesity, the assessment of the expression of pro-inflammatory cytokines, namely, IL-1β and IL-6, as well as anti-inflammatory cytokines, such as IL-10, was critical." (PMID 35741327, 2022). "In obesity, oxidative stress linked with alteration of the immune system and with ultimate aberrant cell signaling, stimulated cell growth and angiogenesis is promoted via enhanced inflammatory factors and adipokines (TNF, leptin, IL-1β, and IL-6)." (PMID 35628513, 2022). "Thus, the transcriptional profiles of the TNF-α and IL-1β genes reported in this study agree with the expected inflammatory state characteristics of obesity induced by diet." (PMID 36235679, 2022). "Our group previously showed that, in mice, diet-induced obesity (DIO) caused airway inflammation with elevation of interleukin (IL)-1β levels and AHR, which resembled non-eosinophilic asthma in humans." (PMID 35574481, 2022). "Similarly, platelets from subjects with IR and obesity were found to have an upregulated expression of mRNA for IL-1β and NLRP3 inflammasome." (PMID 35563363, 2022). "Thus, Kupffer cells appear to be a major source for IL-1β in diet-induced obesity in mice and Kupffer cell-derived IL-1β contributed to the development of hepatic steatosis and the ensuing insulin resistance." (PMID 35955975, 2022). "Chronic-low-grade, obesity-associated inflammation activates immune cells preparing the metastatic niche; which then limits immunosurveillance protections, suppressing CD8+ T-cell function through IL-1β, while promoting neutrophil expansion and polarization." (PMID 33815289, 2021).
Obesity (continued). "Moreover, in the future, it would be interesting to understand how ncRNA regulates IL-1β functions at the intersection of inflammation and obesity, particularly in the context of hypertension." (PMID 34445357, 2021). "Furthermore, we uncovered the loss of browning phenotype in PVAT as an important mediator of obesity-induced vascular inflammation and atherosclerosis by exacerbating the production of IL1β, which in turn acts in a paracrine manner on the adjacent vessel wall." (PMID 34878840, 2021). "IL-22-associated secretion of IL-1β and IL-10 can also stimulate extracellular-signal regulated kinase (ERK) phosphorylation and promote tumor development in collaboration with diet-induced obesity." (PMID 34944732, 2021). "In obesity settings, monocytes exhibit an inflammatory phenotype associated with the increased expression of CD11b, CD11c and HLA-DR surface markers, along with higher secretion of proinflammatory cytokines/chemokines such as TNF-α, IL-6, IL-1β, and MCP-18,10." (PMID 33859296, 2021). "TNFα and IL-1β are the main obesity-induced proinflammatory cytokine and chemokine, respectively." (PMID 34531738, 2021). "The regulation of IL-1β expression by RNA interference could be an effective approach for the treatment of high-fat induced obesity, since gene therapy is a potential way for disease treatment and tissue function recovery." (PMID 34683827, 2021). "Moreover, circulating pro-inflammatory IL-1β increased with gestation in lean mothers but remained unchanged in mothers with obesity." (PMID 34195568, 2021). "Yeast microcapsules mediated IL-1β shRNA delivery can effectively improve obesity." (PMID 34683827, 2021). "For instance, in type II diabetes, the aberrant activity of the NLRP3-inflammasome complex leads to IL1β secretion and caspase-1 activation that impair pancreatic β-cell function, adipocyte function and insulin sensitivity, promoting obesity and insulin resistance." (PMID 34685542, 2021). "However, the role of the NLRP3 inflammasome in IL-1β release through GSDMD pores during obesity-induced IR in skeletal muscle tissue remains unexplored." (PMID 34638553, 2021). "Thus, the aberrant release of IL1β is involved in the pathogenesis of a range of inflammatory diseases, such as gout, type II diabetes, atherosclerosis, obesity, heart failure, recurrent pericarditis, rheumatoid arthritis and smoldering myeloma." (PMID 34685542, 2021). "Multiplex analysis of circulating cytokines revealed increases in IL1b and TNFa with early obesity." (PMID 34330904, 2021). "A recent study performed on human subjects diagnosed with obesity further supports that the progression of hypertension may be influenced or regulated by the IL-1β pathway." (PMID 34445357, 2021). "In addition, obesity induces NLRC4/IL-1β-dependent upregulation of angiopoietin-like 4, leading to increased angiogenesis and growth in tumors in mice." (PMID 34944905, 2021). "Moreover, inflammatory markers that allow monitoring of obesity and MetS include proinflammatory cytokines production such as TNF-α, IL-1β, and IL-6, which are mainly produced by the macrophages infiltration induced by obesity in the adipose tissue." (PMID 32178436, 2020). "Additionally, Blautia has been described to exhibit closely positive correlation with TG, TC, IL-6, TNF-α and IL-1β, linking to hepatic lipogenesis and obesity." (PMID 33390939, 2020). "In mouse models, genetic or pharmacological inhibition of NLRP3 activation pathways or IL-1β prevents adipose tissue dysfunction, including inflammation, fibrosis, defective lipid handling and adipogenesis, which in turn alleviates obesity and its related metabolic disorders." (PMID 32545355, 2020). "In sum, these results have suggested that activation of NLRP3-inflammasome/IL-1β signalling could activate neuroinflammatory response and impair synaptic plasticity, leading to cognitive impairment in diet-induced obesity or diabetic condition." (PMID 33379163, 2020).